POLQ (DNA polymerase theta)
Diseases named in the same sentence as POLQ in open-access papers (continued):
Sharing a sentence is not in itself a finding about the gene and the disease.
lung carcinoma (continued). "Since analysis of data from the TCGA dataset revealed an association of increased POLQ expression with an increased somatic mutation load in LAC, we investigated whether POLQ overexpression actually induced mutations in the lung cancer cell clones established by us." (PMID 31137743, 2019). "POLQ, BRCA2, ATM, ATR, PARP4, and POLD1 alterations were most commonly observed in the entire advanced lung cancer cohort." (PMID 34604048, 2021). "Overexpression of the specialized DNA polymerase theta (POLQ) is frequent in breast, colon and lung cancers and has been correlated with unfavorable clinical outcomes." (PMID 34206946, 2021). "In the lung cancer, the driver triad hsa_circ_0051620| SLC1A5–hsa-miR-338-3p—CDH2 and hsa_circ_0066954| POLQ–hsa-miR-338-3p—CDH2 shows the downregulation of the driver gene CDH2, which increases the survival of the patients." (PMID 34055888, 2021). "Consistently, the co-knockdown of FANCD2 and POLQ in two lung cancer cell lines resulted in hypersensitivity to cisplatin, as compared with the single knockdown of FANCD2 or POLQ." (PMID 34206946, 2021). "Since POLQ overexpression was detected in LAC, the effects of POLQ overexpression in lung cancer cell line-derived clones were also investigated." (PMID 31137743, 2019). "Another study showed that DNA polymerase theta (POLQ) overexpression was positively correlated with PLK4 overexpression in lung adenocarcinoma and induced PLK4-mediated centrosome amplification in lung cancer cells." (PMID 41488365, 2025). "Similarly, in lung cancer, the circRNAs, namely, hsa_circ_0051620| SLC1A5 and hsa_circ_0066954| POLQ, are upregulated and are shown to interact with and regulate driver genes, namely, ADAM17, CDH2, RUNX2, and ZBTB18, through miR-338-3p." (PMID 34055888, 2021).
colorectal cancer (8 papers, 2010 to 2025). A primary or metastatic malignant neoplasm that affects the colon or rectum. "Previous study showed that POLQ was associated with a concomitant overexpression of firing genes that were significantly related to poor prognosis of colorectal cancer patients." (PMID 34517891, 2021). "Regrettably, few studies have investigated the function of POLQ in colorectal cancer and its regulation of tumor progression." (PMID 39520627, 2024). "Previous studies have reported that the level of POLQ expression is distinctly upregulated in colorectal cancer (CRC), but little attention has been given to its function and regulation of CRC progression." (PMID 39520627, 2024). "The transcription and expression of POLQ are significantly up-regulated in colorectal cancer tissues and cells." (PMID 39520627, 2024). "Increased expression of POLQ has also been detected in many kinds of tumours, such as lung cancer, colorectal cancer and gastric cancer." (PMID 35726713, 2022). "Positive correlations between expression levels of POLQ and HR genes have recently been reported in lung, breast and colorectal cancers." (PMID 29283884, 2017). "Therefore, we used it to further explore the relationship between POLQ and the cell cycle signaling pathway in promoting the progression of colorectal cancer." (PMID 39520627, 2024). "Finally, we report that POLQ expression correlates with the expression of a set of HR genes in breast, lung and colorectal cancers." (PMID 27612511, 2016).
breast tumors (7 papers, 2010 to 2022). "Furthermore, a recent study identified a novel druggable target, DNA polymerase theta (POLQ), which is highly expressed in HR-deficient ovarian and breast tumor." (PMID 36284291, 2022). "The development of multiple primary breast tumors (bilateral breast tumor) can be associated to disrupted POLQ expression that may be involved in DSB repair." (PMID 25409685, 2014). "In breast tumors, POLQ overexpression is considered to favor the emergence and survival of proliferating cancer cells." (PMID 34335688, 2021). "It is noteworthy that POLQ is highly expressed in breast tumors and this expression is able to predict patient outcome." (PMID 25409685, 2014). "Essentially, ZEB1 and POLQ expression are mutually exclusive in breast tumors." (PMID 34458275, 2021). "Moreover, POLQ is upregulated in a range of human cancers, and indicates a poor clinical prognosis, especially in breast tumours." (PMID 27131361, 2016). "POLQ expression is upregulated in a large proportion of breast tumour samples." (PMID 20700469, 2010). "Moreover, a recent synthetic lethality screen uncovered 140 genes that have a synthetic growth defect with POLQ, most of which operate outside of DSB repair, and showed that as much as 30% of breast tumors may be relying on Pol θ for survival." (PMID 33750946, 2021).
lung adenocarcinoma (7 papers, 2019 to 2025). A carcinoma that arises from the lung and is characterized by the presence of malignant glandular epithelial cells. "Co-expression of PLK4 and POLQ caused polyploidy where POLQ may have contributed to resistance to DSBs and promoted cancer progression in lung adenocarcinoma." (PMID 41488365, 2025). "Somatic mutations of multiple MMR genes as well as POLE, POLQ, ATM, and ATR were significantly associated with higher neoantigen loads in UCEC, BRCA, lung adenocarcinoma (LUAD), and STAD (FDR < 1.2 × 10−5)." (PMID 34095878, 2021). "It will be important to examine the efficacy of CHK1 inhibitors in combination with either RAD51 or POLQ small molecules when treating MYBL2 High lung adenocarcinomas." (PMID 33489883, 2020). "In this study, we demonstrate that MYBL2 High lung adenocarcinomas upregulate transcriptional programs that coordinate replication stress responses and POLQ-mediated error-prone repair despite containing BRCA proficient pathways." (PMID 33489883, 2020). "Overexpression of POLQ increased somatic mutation load and Polo-like kinase 4 (PLK4) overexpression, which induces centrosome amplification and is associated with an advanced pathologic stage in lung adenocarcinoma." (PMID 39520627, 2024). "In the present study, we examined whether abnormal POLQ expression may be involved in the pathogenesis of lung adenocarcinoma (LAC)." (PMID 31137743, 2019).
ovarian carcinoma (7 papers, 2016 to 2025). A malignant neoplasm originating from the surface ovarian epithelium. "Here, we find that ALDH1A1 enhances the expression of DNA polymerase θ (Polθ, encoded by the POLQ gene) in ovarian cancer cells." (PMID 37429899, 2023). "In addition, POLQ levels were found to be remarkably high in homologous recombination (HR)-deficient breast and ovarian cancers and correlated with unfavorable clinical outcomes." (PMID 34206946, 2021). "Indeed, in HR-deficient ovarian cancer cell lines POLQ was selectively upregulated, whereas restoration of HR brought back POLQ expression to normal levels." (PMID 33195396, 2020). "The upregulation of POLQ/Polθ by ALDH1A1 is further confirmed in another ovarian cancer cell line Kuramochi." (PMID 37429899, 2023). "In summary, we demonstrated that ALDH1A1 facilitates the production of RA, which activates the transcription of POLQ via binding to the RAR at the RARE in the promoter region of the POLQ gene, thereby enhancing MMEJ and leading to PARPi resistance in HR-deficient ovarian cancer cells." (PMID 37429899, 2023). "To test this hypothesis, we first activated or inhibited the RAR using its selective agonist CH55 or antagonist AGN 193109, respectively, and examined the expression of POLQ/Polθ in a panel of ovarian cancer cell lines." (PMID 37429899, 2023). "Our findings affirm the pro-cancer role of iron in ovarian cancer and reveal that iron advances platinum resistance by promoting DNA damage repair through FTH1/FTL/POLQ/RAD51 pathway." (PMID 38740757, 2024). "Next, we sorted ALDH-dim and ALDH-bright (ALDH-br) cell subpopulations from two ovarian cancer cell lines PEO1 and OVCAR3, and validated the enhanced expression of POLQ at the mRNA level in ALDH-br cells compared to ALDH-dim cells using qRT-PCR." (PMID 37429899, 2023). "It has also been reported that double knockdown of POLQ and FANCD2 decreased the tumor volumes of xenotransplants of a human ovarian cancer cell line." (PMID 34206946, 2021). "Therefore, we hypothesized that iron suppresses POLQ expression to enhance RAD51 mediated DNA repair, thus ultimately reducing the sensitivity of ovarian cancer to platinum." (PMID 38740757, 2024).
gastric cancer (6 papers, 2017 to 2024). A primary or metastatic malignant neoplasm involving the stomach. "Only the gene expression of POLQ (catalytic subunit of Polθ) was significantly associated with mutation induction in stomach cancers." (PMID 28582771, 2017). "High rate of A→G mutations led to an increase of the fraction of A→G mutations in stomach cancers with high-expression POLQ." (PMID 28582771, 2017). "This work suggests that the combination of POLQ inhibitor and ferroptosis inducer synergistically kill gastric CSCs and thus provides a new therapeutic strategy for gastric cancer." (PMID 38575587, 2024). "Our results identify a POLQ-mediated stemness and ferroptosis defense mechanism and provide a new therapeutic strategy for gastric cancer." (PMID 38575587, 2024). "Herein, we found that POLQ positively regulates stem cell-like characteristics and ferroptosis resistance of gastric cancer cells." (PMID 38575587, 2024). "Polymerase theta (POLQ), a DNA polymerase, drives resistance to ferroptosis in gastric cancer cells by stimulating DHODH expression via the transcription factor E2F transcription factor 4 (E2F4)." (PMID 39624080, 2024). "By inhibiting POLQ, we effectively weakened the stemness and antioxidant capacity of gastric cancer cells, consequently heightening their sensitivity to ferroptosis." (PMID 38575587, 2024). "In our study, we made a significant discovery regarding the role of POLQ in regulating the stemness of gastric cancer cells." (PMID 38575587, 2024). "The combination of POLQ inhibitor and ferroptosis inducer has synergistic inhibitory effects on gastric cancer stem cells, providing a potential clinically feasible strategy for gastric cancer." (PMID 39624080, 2024). "In this novel study, we demonstrated, for the first time, that alterations in POLQ levels impact the phenotype and behavior of stemness characteristics in gastric cancer." (PMID 38575587, 2024). "Intriguingly, our study also revealed an additional effect of POLQ inhibitors—reducing the stemness of gastric cancer cells." (PMID 38575587, 2024). "We screened eight DDR-related genes (ZBTB7A, POLQ, CHEK1, NPDC1, RAMP1, AXIN2, SFRP2, and APOD) to establish a risk model, which can predict the prognosis of gastric cancer patients and guide the clinical implementation of immunotherapy." (PMID 36578802, 2022). "Consistent with it, the mutation rates of the six types of base substitutions were all significantly increased in stomach cancers with high-expression POLQ." (PMID 28582771, 2017). "Future studies can examine the POLQ knockdown in stomach cancer cell lines with concurrent defects of POLD1 and POLE." (PMID 28582771, 2017). "Furthermore, we found that POLQ expression correlated with resistance to ferroptosis, and POLQ inhibition renders gastric cancer cells more vulnerable to ferroptosis." (PMID 38575587, 2024). "Here, we show that POLQ positively regulates stem cell-like characteristics of gastric cancer cells, knockdown of POLQ suppressed the stemness of GC cells in vitro and in vivo." (PMID 38575587, 2024). "Therefore, we hypothesized that POLQ regulates stemness in gastric cancer cells by modulating the expression of DHODH." (PMID 38575587, 2024). "Further investigation revealed that POLQ regulated DHODH expression via the transcription factors E2F4, thereby regulating ferroptosis resistance and stemness of gastric cancer cells." (PMID 38575587, 2024). "Since pharmacological inhibition of POLQ attenuates the stemness of GC cells and sensitizes gastric cancer to ferroptosis, we further investigated the therapeutic potential of combined treatment with POLQ inhibitors and ferroptosis inducers in treating gastric tumors in vivo." (PMID 38575587, 2024).
pancreatic cancer (6 papers, 2023 to 2026). "There are some reports regarding mutations in the POLQ gene, all found in familiar pancreatic cancer and in the undifferentiated sarcomatoid carcinoma, but both represent the minority of the cases." (PMID 39435280, 2024). "We also observed increased cytosolic micronuclei formation in HR-deficient pancreatic cancer cells with POLQ inhibition and subsequent activation of the cGAS-STING pathway." (PMID 36976649, 2023). "Our results indicated that high POLQ H-score was associated with poor survival, therefore, POLQ could be considered an independent prognostic factor for patients with pancreatic cancer." (PMID 39435280, 2024). "In this study, we demonstrated, for what we believe to be the first time, that POLQ is a promising therapeutic target in HR-deficient pancreatic cancer using short hairpin RNA-mediated (shRNA-mediated) downregulation in both human and murine models of HR-deficient PDAC." (PMID 36976649, 2023). "Thus, we demonstrate for the first time that POLQ is a promising target in HR-deficient pancreatic cancer and its role in eliciting cGAS-STING signaling." (PMID 36976649, 2023). "VUS of LS-related germline MMR genes and POLQ were significantly associated with pancreatic cancer." (PMID 36896836, 2023). "To investigate whether stable knockdown of POLQ would suppress in vivo growth of HR-deficient pancreatic tumors, we orthotopically implanted KPC and KPC-Brca2–/– cells with POLQ knockdown into the pancreata of syngeneic C57BL/6J mice." (PMID 36976649, 2023). "In addition, it was shown that POLQ promotes the survival of cells deficient in homologous recombination genes, where a synthetically lethal correlation was revealed, even very recently in pancreatic cancer cells." (PMID 39435280, 2024). "Further, we show that POLQ inhibition causes the accumulation of cytosolic DNA to activate the cyclic GMP-AMP synthase–stimulator of interferon genes (cGAS-STING) signaling pathway in BRCA2-deficient pancreatic tumors, thus enhancing intratumoral T cell infiltration." (PMID 36976649, 2023). "In this report we evaluate the usefulness of POLQ expression analysis for outcome prediction in pancreatic cancer." (PMID 39435280, 2024). "Our results indicate that POLQ is an independent prognostic factor in pancreatic cancer when analyzed by immunostaining, which is in agreement with the results shown by the POLQ gene expression analysis (GEPIA)." (PMID 39435280, 2024). "Despite evidence reported in other tumors, there is little data regarding either the impact of POLQ in pancreatic cancer, or the usefulness of immunohistochemistry staining of POLQ as a valuable technique to associate its expression level with patient outcome." (PMID 39435280, 2024). "Due to the fact that its role as a biomarker in pancreatic cancer remains unexplored, we aimed to study the usefulness of POLQ H-score as a prognostic factor in a pancreatic cancer patient cohort." (PMID 39435280, 2024). "Here, we extend the POLQ-HR synthetic lethal interaction to pancreatic cancer cells and report a synthetic lethal interaction between ATM and POLQ." (PMID 36976649, 2023).
pancreatic cancer (continued). "Overall, these data support that, in addition to synthetic lethality between POLQ and BRCA2, cytosolic DNA damage products that accumulate in the presence of POLQ inhibition activate cGAS-STING signaling in BRCA2-deficient pancreatic cancer cells." (PMID 36976649, 2023). "Our results indicate that the POLQ H-score obtained from immunohistochemistry is a valuable prognostic biomarker for pancreatic cancer outcomes, which may also contribute to the future design of more personalized therapies that improve patient prognoses." (PMID 39435280, 2024). "Although the other variants in BRCA1, ATM, and POLQ were not previously reported and were identified as novel variants in this current study, pathogenic variants in these genes have also been reported in pancreatic cancer and therefore these genes have been known to cause PDAC." (PMID 37234870, 2023).
colon cancer (5 papers, 2018 to 2024). "Masuda revealed that higher relative POLQ expression was found in various cancers including stomach, lung, and colon cancer, and discovered poor prognosis in patients with POLQ overexpression." (PMID 39520627, 2024). "A comparison of POLQ mRNA in tumor tissues and matched control tissues from the same individuals showed higher relative POLQ expression in stomach, lung and colon cancers." (PMID 29301327, 2018). "Four ESCC cell lines, namely, KYSE70TS, KYSE180TS, 81T and SLMT, had higher POLQ expression levels even when compared with RKO, a colon cancer cell line well-known for expressing high endogenous levels of POLQ." (PMID 34206946, 2021).
hepatocellular carcinoma (5 papers, 2021 to 2025). A malignant tumor that arises from hepatocytes. "Moreover, Qi indicated that POLQ knockdown interferes with the development and progression of hepatocellular carcinoma by regulating cell proliferation, apoptosis, and migration." (PMID 39520627, 2024). "In addition, IHC performed in Hepatocellular carcinoma (HCC) samples also showed that POLQ was expressed higher than in normal tissues." (PMID 39435280, 2024). "DNA Polymerase Theta (POLQ) is a DNA polymerase involved in error-prone translesion DNA synthesis (TLS) and error-prone repair of DNA double-strand breaks (DSBs), whose function in hepatocellular carcinoma has not been investigated." (PMID 34517891, 2021).